AKT3 (AKT serine/threonine kinase 3)
Diseases named in the same sentence as AKT3 in open-access papers (continued):
Sharing a sentence is not in itself a finding about the gene and the disease.
lung cancer (16 papers, 2014 to 2025). A malignant neoplasm involving the lung. "High expression of AKT1, AKT2 and AKT3 was significantly associated with a OS in patients with clinical stage I lung cancer, and high expression of AKT3 was also found to be associated with a reduced OS in patients with clinical stage II lung cancer." (PMID 36945793, 2022). "We report that Akt1 ablation inhibits the incidence and development of lung tumors, Akt2 deficiency markedly accelerates lung tumor initiation and Akt3 ablation slightly enhances tumor progression in this mouse model of lung cancer." (PMID 24722238, 2014). "However, loss of Akt3 had a more dramatic impact on tumor multiplicity and size in the K-ras- and carcinogen-induced lung cancer models than it did in our model." (PMID 24722238, 2014). "Furthermore, high AKT3 mRNA expression was associated with a poor OS in patients with lung cancer (HR, 1.31; 95% CI, 1.16–1.49; P=2.2e−05) and patients with LUAD (HR, 2.08; 95% CI, 1.64–2.64; P=7.9e−10), but not in patients with SqCLC (HR, 0.97; 95% CI, 0.77–1.23; P=0.82)." (PMID 36945793, 2022). "Western blot analyses revealed pronounced reduction of E-cadherin and NCAM in the Akt3-kd cells, whereas Akt1 and Akt2 depletion upregulated E-cadherin, especially in H23 lung carcinoma cells." (PMID 38291468, 2024). "Circ-AKT3 is upregulated in lung cancer tissues and cells, and knockdown of circAKT3 improves the cell sensitivity to CDDP and reduces glycolysis." (PMID 36338714, 2022). "After knocking out AKT3 in bladder cancer and lung cancer, the mitochondrial oxygen consumption in cancer cells rapidly decrease, indicating that AKT3 plays a vital role in the normal respiration of cancer cells." (PMID 35903358, 2022). "Circ AKT3 inhibits the cisplatin sensitivity of lung cancer cells via the miR-516b-5p/STAT3 axis-mediated glycolysis balance." (PMID 36338714, 2022). "Of these, genes such as DUSP4 and AKT3 are well documented as being involved in smoking-related lung cancer." (PMID 28500316, 2017). "In lung cancer, AGTR1 inhibits the progression of lung adenocarcinoma by promoting the PI3K/AKT3 pathway." (PMID 36983741, 2023). "The expression of Akt3 is more divers, with five pancreatic and two lung carcinoma cell lines showing no or hardly detectable protein bands." (PMID 38291468, 2024). "Besides, highly phosphorylated PDGFRA has been observed in non‒small cell lung cancer and rhabdomyosarcoma, AKT2 and AKT3 are the serine/threonine kinases that regulate cellular metabolism, cell proliferation, cell survival, cell growth and angiogenesis." (PMID 35399006, 2022). "In addition to the similar CNV profile (e.g., common gains in chromosomes 1, 8, 17, and 20) and gene expression profile (e.g., overexpression of AKT3, MYC) between the breast tumor samples and the ovary/lung cancer cell lines, there are some other commonalities between them." (PMID 26273658, 2015). "Additionally, AKT3, but not AKT2 depletion, was found to inhibit proliferation and survival of lung cancer derived disseminated human tumor cells." (PMID 24946858, 2014).
thyroid cancer (15 papers, 2017 to 2023). "In acute myeloid leukemia, miR-29b-1 (part of the miR-29a cluster, and knocked out in the miR-29a-deficient mice) is downregulated, contributing to the loss of normal granulopoiesis, and likewise in thyroid cancer miR-29a appears to be a tumour-suppressor-miR, with loss removing AKT3 regulation." (PMID 28460473, 2017). "Abnormal miR-29/AKT3 axes are found in certain types of human cancer, e.g., miR-29a/AKT3 in thyroid cancer; miR-29b/AKT3 in BC, EOC, and MM; miR-29c/AKT3 in TNBC; and miR-29c-3p/AKT3 in BC." (PMID 37998329, 2023). "The expression of AKT3 mRNA was reduced in thyroid cancer tissues, and an inverse relation was found between the expression of AKT3 and miR-338-3p." (PMID 36313570, 2022). "Circ_0000144 had been uncovered to accelerate malignant behaviors of thyroid cancer via elevating AKT3 expression by adsorbing miR-217." (PMID 35902926, 2022). "In literature, several papers reported that miR-145 is downregulated in thyroid cancer where it acts as a tumor suppressor by impairing cancer cell growth, cell motility, and metastasis through targeting AKT3 and RAB5C genes or by regulating the NF-κB pathway." (PMID 35222800, 2022). "For example, miR-338-3p has been found to inhibit thyroid cancer cell growth through direct targeting of AKT3." (PMID 34429400, 2021). "miR-497 and miR-375 were demonstrated to be down-regulated in thyroid cancer and target AKT3 and ErbB2 receptor tyrosine kinase 2 (ERBB2), respectively." (PMID 33158279, 2020). "A previous study showed Akt signaling was inhibited after miR-145 overexpression in thyroid cancer cells, while AKT3 is a target of miR-14521." (PMID 31160577, 2019). "Recently, it was found that the expression of AKT3 was upregulated in thyroid cancer and that the inhibition of AKT3 inhibited it’s proliferation." (PMID 30186040, 2018). "MicroRNA-338-3p is down-regulated in thyroid cancer tissues and inhibits the progression of thyroid cancer by repressing AKT3 expression." (PMID 30186040, 2018). "Akt3-promoted tumor progression in cancers of the thyroid and liver has been controversial." (PMID 34591413, 2021). "The AKT3 up-regulation, caused by miR-497 down-regulation, resulted in the activation of PI3K/Akt pathway that eventually promotes proliferation and invasion in thyroid cancer." (PMID 33158279, 2020). "These included ABL1 and the master regulator NKX2-1 in thyroid cancer, ERBB3 in liver cancer and AKT3 in colorectal adenocarcinoma." (PMID 35725412, 2022). "AKT3 is one of the three isoforms of the AKT family and its overexpression has been reported in breast, prostate, and thyroid cancers." (PMID 33833996, 2021).
hemimegalencephaly (12 papers, 2014 to 2025). "Dysregulation of mTOR signaling can cause a variety of diseases, including tuberous sclerosis (mutations in TSC1, TSC2), hemimegalencephaly (AKT3, PIK3CA, MTOR) and focal cortical dysplasia (DEPDC5, AKT3, MTOR)." (PMID 26302787, 2015). "AKT3 controls brain size, and research has shown that genetic variation (duplication and point mutation) of AKT3 contributes to hemimegalencephaly." (PMID 24901509, 2014). "ENS arises from activating mutations in PIK3CA or AKT3, which drive hyperactivation of the PI3K-AKT–mTOR signaling axis, clinically manifesting as epidermal nevi, hemimegalencephaly, and drug-resistant epilepsy." (PMID 40979205, 2025). "Activating germline and somatic AKT3 mutations has also been described in a small number of individuals with atypical MPPH and hemimegalencephaly (MPPH2 [MIM 615937])." (PMID 25972378, 2015). "Furthermore, somatic mosaic mutations in genes such as TSC2 or AKT3 drive PI3K-AKT–mTOR pathway overactivation, inducing focal cortical dysplasia or hemimegalencephaly-critical epileptogenic substrates." (PMID 40979205, 2025).
Anxiety (11 papers, 2013 to 2024). Intense feelings of nervousness, tension, or panic often arise in response to interpersonal stresses. "The loss of Akt3 function induces depressive and anxiety-like behaviors as well as learning and memory deficits." (PMID 32325885, 2020). "We also measured time spent in the center of the apparatus to assess if Akt3 deficiency is associated with anxiety-like phenotypes." (PMID 28467426, 2017). "Our results in two antidepressant-sensitive tests, the force swim and TSTs, and three anxiogenic tests, the open field, the elevated plus maze and the dark-light tests, suggest that deletion of Akt3 increases susceptibility to develop symptoms related to depression and anxiety." (PMID 28442992, 2017). "AKT3 has shown effects on anxiety, spatial-contextual memory, and fear extinction in mice, and loss-of-function of AKT3 causes learning and memory deficits." (PMID 38036788, 2023). "Male and female mice with single-isoform deletions of Akt1, Akt2, or Akt3 were assessed for anxiety-related behaviors in the open field arena (OFA) and elevated plus maze (EPM) tests." (PMID 33325370, 2020). "To verify the effect of a chronic treatment on the depressive and anxiety-like phenotypes observed in Akt3 KO mice, we used the mood stabilizer lithium." (PMID 28442992, 2017). "For instance, while Pdyn is the only gene positively correlated with anxiety-like behavior in XX mice, Htr1a, Cdk5, Adcy2, Akt1, Akt2, and Akt3 positively correlate with anxiety-like behavior in XY- mice." (PMID 24199867, 2013). "Lithium treatment also rescued depressive and anxiety-like behaviors in AKT3-knockout mice." (PMID 35525984, 2022). "Notably, chronic administration of lithium, a mood stabilizer, restored the decreased phosphorylated GSK3α/β levels and rescued the depressive and anxiety-like behaviors in the Akt3 KO mice." (PMID 28442992, 2017). "Notably, in our experiments, the chronic lithium treatment known to amplified GSK3α phosphorylation at serine 21 and GSK3β at serine 9, is able to reverse the behavioral signs of anxiety and depression observed in Akt3 KO mice." (PMID 28442992, 2017). "Interestingly, overexpression of AKT3 in PTEN-null PC-3 mCRPC cells can promote proliferation and tumor growth in vivo, whereas systemic deletion of Akt3 has been shown to trigger neurological conditions, including depressive and anxiety-like behaviors in mice." (PMID 33105713, 2020). "This may explain the synergistic effects of Akt1 and Akt3 removal on memory and why Akt1 removal alone was sufficient to affect anxiety-like behavior and fear extinction: GABAergic mechanisms linked to interneuronal function were shown previously to mediate these behaviors." (PMID 33325370, 2020). "When we assessed anxiety-like behavior in Akt1 cKO Akt3 KO mice, we found no performance differences in the OFA or EPM compared to WT controls for either sex." (PMID 33325370, 2020). "In Akt3 KO mice, one earlier study reported increased anxiogenic-like EPM behavior while another reported hyperactivity but no anxiety-like behavioral alterations." (PMID 33325370, 2020).
colon cancer (10 papers, 2014 to 2026). "In colon cancer cells, activation of AKT1 and AKT3 results in the abnormal suppression of miR-125b-5p, which subsequently leads to the upregulation of GLUT5 expression, causing metastasis and drug resistance in colon cancer cells." (PMID 41584038, 2026). "Besides, AKT3 enhanced migration and induce drug resistance in colon cancer cells by mediating miR-125b-5p." (PMID 36843983, 2023). "Furthermore, the targeted inhibition of AKT1 and AKT3 prevented glycolysis-related enzyme activation, significantly blocked the production of lactate and diminished the migration and invasion of chemoresistant colon cancer cells." (PMID 38396845, 2024). "Notably, overexpression of PHLPP2, as well as the inhibition of miR-141 or miR-424 could inhibit the proliferation, migration, invasion, and EMT of colon cancer cells by inhibiting the activation of the Akt3-p27 pathway." (PMID 32633726, 2020).
atherosclerosis (9 papers, 2014 to 2022). A disease characterized by the build-up of fatty material and calcium deposition in the arterial wall resulting in partial or complete occlusion of the arterial lumen. "Researchers reported that, in apoE-deficient mice, the loss of Akt1 leaded to severe atherosclerosis and Akt3 deficiency in macrophages promoted foam cell formation and atherosclerosis." (PMID 35151267, 2022). "Some of these genes such asSPP1, TGFB, and AKT3 have been associated with atherosclerosis in previous studies on mice and human samples, thus supporting our findings." (PMID 35488341, 2022). "In contrast, loss of AKT3 in mice induces foam cell formation and atherosclerosis." (PMID 32291381, 2020). "Similarly, Akt3 deficiency in macrophages of Apoe−/− mice promoted foam cell formation and atherosclerosis." (PMID 25240046, 2014). "Although it is mainly expressed in the brain, Akt3 also has a protective function in atherosclerosis." (PMID 35982907, 2022). "This novel approach allowed us to compare the impact of expression of the individual Akt1 and Akt3 isoforms on macrophage viability and atherosclerosis." (PMID 31159424, 2019). "Genetic ablation of Akt3 in ApoE−/− mice led to a 2-fold increase in atherosclerotic lesions, and bone marrow transplantation of Akt3−/−/ApoE−/− to ApoE−/− mice also resulted in a significant increase of atherosclerosis." (PMID 25929188, 2015). "Genetic ablation of AKT3 in macrophages promotes foam cell formation and atherosclerosis in mice." (PMID 32291381, 2020). "Finally, although predominantly expressed in brain, Akt3 also has a protective role in atherosclerosis." (PMID 25929188, 2015). "Macrophages express three Akt isoforms, Akt1, Akt2, and Akt3, but the roles of Akt1 and Akt2 in atherosclerosis in vivo remain unclear." (PMID 25240046, 2014).
depression (9 papers, 2017 to 2024). "Akt has three isoforms, AKT1, AKT2, and AKT3, which play an important role in depression." (PMID 36506595, 2022). "Akt has three subtypes (AKT1, AKT2, and Akt3), which play an important role in depression." (PMID 34479552, 2021). "There are three subtypes of AKT (AKT1, AKT2, and AKT3), and AKT1 is the most important subtype, which plays an important role in depression." (PMID 34257681, 2021).
Insulin resistance (9 papers, 2010 to 2025). Increased resistance towards insulin, that is, diminished effectiveness of insulin in reducing blood glucose levels. "miR-122 was consistently elevated and strongly linked to hepatic insulin resistance, regulating AKT3 and IGF1R." (PMID 41400625, 2025). "Of the three known Akt isoforms (Akt1, Akt2, and Akt3) in insulin-sensitive tissues, defects in Akt2 and Akt3 particularly impair insulin-stimulated glucose transport in insulin resistance." (PMID 39125938, 2024). "We have previously reported insulin resistance dependent decrease in serine phosphorylation of Akt1, Akt2 and Akt3 in neuronal cells.We next proceeded to test the effect of PHLPP1 silencing on Akt isoforms in neuronal insulin signaling and resistance." (PMID 36376971, 2022). "AKT3 has been reported to be related to neuronal insulin resistance in neurodegenerative diseases." (PMID 35528544, 2022). "Thus, the interaction between AKT3, WNK1 and SGK1 regulates adipogenesis in vivo, and dysregulation of this pathway can lead to increased adipogenesis and obesity as well as insulin resistance." (PMID 35880040, 2022).
bladder cancer (8 papers, 2016 to 2022). "AKT3 rs2994329 was shown to significantly increased bladder cancer risk, while AKT3 rs12045585 exhibited reverse association." (PMID 26828791, 2016). "A study conducted among Caucasians reported that two SNPs in the AKT3 gene had profound effects on bladder cancer susceptibility." (PMID 26828791, 2016). "Therefore, we speculate that AKT3 may participate in proliferation and apoptosis of bladder cancer cells through these pathways, and ultimately affect the biological behavior of tumor cells." (PMID 32047516, 2019). "This pathway is activated in around 40% bladder cancer cases (FGFR3: > 10%, EGFR:> 10%, ERBB2:~ 10%, ERBB3:~ 10%, NRAS/HRAS/KRAS:~ 10%, PTEN: ~ 10%, AKT3:~ 10%)." (PMID 31665050, 2019).
cardiac hypertrophy (8 papers, 2020 to 2025). "For instance, in cardiac hypertrophy, CHRF interacts with miR-93 and miR-489 to regulate AKT3 and MyD88, promoting myocardial hypertrophy." (PMID 40612103, 2025). "Its downregulation has been shown to mitigate myocardial ischemia, reperfusion injury, and cardiac hypertrophy post-acute myocardial infarction by influencing the miR-2054/AKT3 and miR-204-5p/LGALS3 pathways." (PMID 41169895, 2025). "AKT3 plays a crucial role in the mechanism by which CM‐specific mir15a/mir16‐1 knockout promotes cardiac hypertrophy and dysfunction after TAC." (PMID 39900554, 2025). "Research indicates that CHRF is upregulated in Iso-induced myocardial hypertrophy models and promotes hypertrophy through the miR-93/AKT3 axis in stimulated cardiomyocytes." (PMID 40612103, 2025). "The authors were able to demonstrate that the high-expression of CHRF can sponge miR-93 expression and impact cardiac hypertrophy by altering Akt3 expression, even if pathway-specific regulatory effects remain to be further elucidated." (PMID 32605220, 2020). "For example, KCNQ1OT1 depletion could suppress cardiac hypertrophy by sponging miR-2054 and decreasing AKT3 expression." (PMID 36100884, 2022). "During hypertrophic stress, increased C/EBPβ downregulates the mir15a/mir16‐1 cluster, resulting in up‐regulation of multiple target proteins (INSR, IGF1R, AKT3, SGK1) in cardiomyocytes, causing increased activation of insulin/IGF1 signaling, ultimately causing cardiac hypertrophy and dysfunction." (PMID 33377640, 2020). "In the CHRF/miR-93/AKT3 Axis, CHRF promotes myocardial hypertrophy in cardiac hypertrophy through this regulatory pathway." (PMID 40612103, 2025). "Taken together, these data suggest INSR, IGF1R, AKT3 and SGK1 are novel target genes contributing to mir15a/mir16‐1 inhibition‐mediated cardiac hypertrophy." (PMID 33377640, 2020). "Akt3 was selected as it was found in the overlap among the protein-coding genes putative miR-93 targets and the PI3K/Akt signaling pathway—crucial regulators in the progression of cardiac hypertrophy." (PMID 32605220, 2020).
Obesity (8 papers, 2018 to 2025). Accumulation of substantial excess body fat. "MAPK and PI3K-AKT pathways were overexpressed, and Mapk1 and Akt3 genes were common crossing points among obesity-associated disorders' pathways." (PMID 39484291, 2024). "Several of the high-scoring genes (score ≥ 11) are known to be implicated in obesity (such as DGKI [score: 22.8], MC4R [19.6], BDNF [19.6], MTOR [16.8], SH2B1 [14.8], GIPR [14.3], AKT3 [11.6], and LEPR [11.6])." (PMID 38754426, 2024). "We found that Akt3 is a cross point in the PPI networks deregulated in the VAT of patients with obesity." (PMID 39484291, 2024). "The interconnection of these pathways through Mapk1 and Akt3 in the VAT of patients with obesity was also demonstrated; to our knowledge, this is the first peer-reviewed report of a transcriptomic analysis that establishes these molecules as crossing points in the complex pathogenesis of obesity." (PMID 39484291, 2024). "In the IPP networks, the presence of Akt3 and Mapk1 mediators as crossover points among pathogenic pathways was consistent, suggesting the crucial role of PI3K/AKT and MAPK signaling pathways commanding the complex pathogenesis of obesity." (PMID 39484291, 2024). "The results here showing RIZ1 regulation of histone methylation on Akt3 promoter may help elucidate the link between histone methylation and cancer/obesity." (PMID 29367689, 2018). "In addition, Akt3 inhibits adipogenesis and protects against diet-induced obesity." (PMID 32325885, 2020). "All these results indicate that AKT3 is a target of RIZ1 regulation, thereby expanding our understanding of the AKT pathway in cancer and obesity." (PMID 40867614, 2025). "RIZ1 is an essential regulator of AKT3 transcription and AKT phosphorylation, suggesting a role for RIZ1 in high-fat diet-induced obesity and the AKT pathway." (PMID 40867614, 2025). "To better understand the role of RIZ1 in obesity and cancer, we investigated how RIZ1 regulates the expression of Akt3." (PMID 29367689, 2018). "Since RIZ1 KO mouse exhibit diet-induced obesity and higher body weight, the link between RIZ1 and Akt3 found here may also play a role in obesity related pathways." (PMID 29367689, 2018).